CRP (C-reactive protein)
Diseases named in the same sentence as CRP in open-access papers (continued):
Sharing a sentence is not in itself a finding about the gene and the disease.
cancer (continued). "Recently, the CRP/Alb ratio was reported to correlate with prognosis in patients with various cancers, including EC." (PMID 29262582, 2017). "Recent studies have shown inflammation-based prognostic scores, including Glasgow prognostic score (GPS), modified Glasgow prognostic score (mGPS), and CRP/Albumin (C/A) ratio to be a significant prognostic indicator in many cancers, including EC." (PMID 28740506, 2017). "Multivariate analysis of these 541 patients after adjustment for other variables including cancer stage, CRP/Alb ratio was an independent prognostic factor for DFS of patients in full resection of localized RCC (P = 0.008)." (PMID 28264659, 2017). "Further studies are needed to clarify the relationship between the BNP and CRP levels in “ab initio”-non-cancer patients validated by the systemic screening tests." (PMID 28570595, 2017). "Inflammatory cytokines such as IL-6, CRP, and TNF-alpha have been shown to be associated with cancer incidence." (PMID 29045425, 2017). "During cancer treatment, the increase in circulating concentrations of inflammatory markers, such as C-reactive protein (CRP) and interleukin (IL-6), was related to the development of an overall feeling of fatigue." (PMID 28163706, 2017). "The preoperative C-reactive protein/Albumin (CRP/Alb) ratio has been shown to be valuable in predicting the prognosis of patients with certain cancers." (PMID 28264659, 2017). "Serum concentrations of IL-6 and CRP are positively correlated, and recent evidence suggests that IL-6 also affects cancer cell biology." (PMID 29259311, 2017). "Various types of cancers have been associated with serum amyloid A (SAA), C-reactive protein (CRP) and α1-acid glycoprotein (AGP)." (PMID 28121629, 2017). "C-reactive protein (CRP) is an established biomarker for systemic inflammation, available in most clinical datasets, and provides prognostic information in several cancers including RCC." (PMID 28859644, 2017). "Recently, the CRP/Albumin (CRP/Alb) ratio was reported to correlate with prognosis in various cancers, including EC." (PMID 29262582, 2017). "Because radiation increases CRP in anemic cancer patients and irradiated mice, CRP in the serum was measured in Hemo, RI, and CI mice." (PMID 28934227, 2017). "By time it also became clear, that the systemic inflammatory response plays an important role in the patients nutritional and functional decline, as much that CRP has been added to the definition of cancer cachexia." (PMID 29113384, 2017). "Recently, a number of studies have suggested a potential role for neutrophil-to-lymphocyte ratio (NLR), platelet-to-lymphocyte ratio (PLR), red cell distribution width (RDW) and C-reactive protein (CRP) as simple prognostic markers for a variety of cancers." (PMID 29088839, 2017). "The preoperative C-reactive protein/Albumin ratio (CAR) is valuable for predicting the prognosis of patients with various types of cancers." (PMID 29228679, 2017). "This is the first study to show a significant correlation between elevated serum CRP levels and cancer prognosis in oro-hypopharynx cancer patients treated by radiotherapy." (PMID 29259311, 2017). "Although various factors have been suggested as prognostic indicators in cancer patient, measurements of CRP seem to be a fast, simple and cost-effective predictor in clinical practice." (PMID 29259311, 2017). "Simple analysis revealed that there were significant differences in cancer-specific survival in relation to elevated C-reactive protein (p = 0.011), lymph node status (p < 0.001), UICC stage (p < 0.001), and nEAC (p = 0.005)." (PMID 28740506, 2017). "Recently, a series of inflammatory factors, such as NLR, PLR and C-reactive protein (CRP) were shown to be correlated with a poor prognosis in various types of cancer." (PMID 29113400, 2017).
cancer (continued). "Due to the fact that CRP is an unspecific marker, it is necessary that clinicians rule out other reasons for increased serum CRP before thinking of cancer or tumor recurrence." (PMID 28514756, 2017). "The C-reactive protein/albumin ratio (CAR) has been shown to play a significant prognostic role in several cancers." (PMID 28128229, 2017). "As one of the inflammatory markers, CRP elevation mainly owes to the inflammatory reaction for cancer and surgical procedure." (PMID 29065877, 2017). "The GPS, which takes into account the serum CRP and albumin levels, simply reflects the systemic inflammation status of patients with cancer and their prognosis, as described for various cancer types." (PMID 28717855, 2017). "Previous published studies have shown that serum CRP is a predictor of survival in several cancers, including EC." (PMID 27557504, 2016). "GPS and mGPS are inflammation-based prognostic scores developed by combining CRP and albumin to predict the clinical outcomes in cancer patients." (PMID 26880857, 2016). "The levels of SIR markers, such as the modified Glasgow Prognostic Score (mGPS), the derived neutrophil to lymphocyte ratio (dNLR), platelet levels, CRP levels, and high-sensitive CRP (hs-CRP) have all been found to predict cancer-specific survival." (PMID 27738330, 2016). "C-reactive protein (CRP), fibrinogen, body mass index (BMI), and triglycerides have been associated with the risk and/or progression of cancer and cardiovascular disease." (PMID 27445627, 2016). "Multivariable Cox regression models were used to assess CRP, AGC and G/L ratio in relation to mortality from BCa, all cancer, cardiovascular disease and all causes." (PMID 27294662, 2016). "Of clinical and biochemical features, age at diagnosis, performance status, and the serum level of CRP have been reported as predictors of postoperative cancer recurrence." (PMID 26219992, 2016). "It is significant that in a population of cancer patients with abdominal malignancies, the C-reactive protein, IL-6, nuclear factor-κB, and E-Sel levels in patients with DVT were meaningfully higher than the control group." (PMID 27326361, 2016). "The Glasgow Prognostic score relies on inflammatory biological markers (C-reactive protein and serum Albumin) and predicts survival in advanced cancer." (PMID 26859298, 2016). "Recent studies have demonstrated the prognostic value of the C-reactive protein/albumin (CRP/Alb) ratio in cancer." (PMID 27344157, 2016). "Increased C-reactive protein (CRP) concentrations and accelerated muscle mass loss during chemotherapy cycles have been recently observed in patients with advanced cancer, such as colorectal, biliary and upper gastrointestinal tracts." (PMID 28076611, 2016). "The systemic inflammation-based prognostic factors mainly include GPS, mGPS, CRP/Alb ratio, PLR, and NLR, which were associated with prognosis in various types of cancers." (PMID 27854304, 2016). "By combining the CRP and albumin values, which have both been reported to be independent prognostic factors for various types of cancer, the CRP/ALB ratio is believed to be a more useful marker." (PMID 27812440, 2016). "Based on many recent studies, it is now widely accepted that an elevated CRP value is a reliable indicator of poor prognosis in a variety of types of cancers." (PMID 26880857, 2016). "C‐reactive protein (CRP), an acute‐phase reactive protein produced by hepatocytes, is broadly used for diagnosing inflammation and cancers." (PMID 26799163, 2016). "After adjustment for male gender, history of cancer and HTN, levels of BUN, MCV, sodium, CRP, and ESR and SOFA scores, the all-cause in-hospital mortality rate increased by 21.8 % for each 1 % increase in RDW as a continuous variable." (PMID 27267984, 2016).
cancer (continued). "Nevertheless, we did not observe any alteration in our findings after leptin and CRP were both included in the same analysis, thus suggesting minimal interaction between serum leptin and CRP with respect to cancer mortality as an outcome." (PMID 26632325, 2016). "Clearly, the causal mechanisms of CRP regarding the progression of IHCC and other cancers need to be clarified in further investigations." (PMID 27733196, 2016). "Potential hematological biomarkers representing SIR in cancer patients include C-reactive protein (CRP), albumin, Glasgow Prognostic Score (GPS), modified GPS (mGPS), and neutrophil-to-lymphocyte ratio (NLR)." (PMID 26880857, 2016). "In each different treatment setting, elevated CRP, defined as different cut-off (1.0 or 0.5 mg/dL),was significantly related to worse cancer-specific-survival (CSS)." (PMID 26880857, 2016). "The concentration of adiponectin, another anti-inflammatory cytokine that plays an important role in glucose and lipid metabolism and renders a protective effect against cancer, showed a trend similar to that of CRP." (PMID 26959117, 2016). "C-reactive protein (CRP) is probably the most widely investigated marker of inflammation in the context of cancer detection and prognosis." (PMID 27294662, 2016). "We focused on the impact of serum CRP on the patients’ cancer-specific survival and recurrence-free survival rates." (PMID 27733196, 2016). "We observed a protective effect of leptin against cancer death in women and higher cancer death with increased CRP in men." (PMID 26632325, 2016). "CRP is a representative marker of a systemic inflammatory response and increased CRP is a poor prognostic factor in several cancer types, including RCC." (PMID 27564277, 2016). "An increase in the value of CRP has been demonstrated in patients with inflammatory disease and various cancers." (PMID 27034760, 2016). "In univariate analysis, CRP, albumin, CEA, and CA19-9 were significantly associated with postoperative cancer-specific survival." (PMID 27632196, 2016). "In this study, we aimed to explore the prognostic significance of pre-treatment serum CRP levels on cancer-specific survival (CSS) and recurrence-free survival (RFS) in IHCC patients." (PMID 27733196, 2016). "A cancer-related systemic inflammatory response (SIR), indicated by elevated concentrations of circulating acute phase proteins such as C-reactive protein (CRP), is in various cancer forms associated with worse prognosis." (PMID 27632196, 2016). "Some research has validated that elevated CRP levels have an impact on the growth and progression of cancers, including NPC." (PMID 27854304, 2016). "Inflammation indicators, such as serum ferritin (SF), neutrophil-to-lymphocyte ratio (NLR), lymphocyte-to-monocyte ratio (LMR), platelet-to-lymphocyte ratio (PLR), and C-reactive protein (CRP) have been identified as prognostic indicators in various cancers." (PMID 27833084, 2016). "Clinically, a patient with acute pelvic infection typically presents with fever, chills, leukocytosis and/or increased blood C-reactive protein (CRP), which is distinct from adnexal malignant tumor." (PMID 26894926, 2016). "CRP, which is an acute phase protein, has been widely studied as a prognostic parameter for various cancers." (PMID 27564277, 2016). "As inflammation is important in the progression of human cancer, much attention has been directed to the CRP, an inflammation-related gene." (PMID 26912098, 2016). "GPS was derived from the acute-phase proteins C-reactive protein and albumin, which were more sensitive and reliable markers that reflect the systemic inflammatory response in cancer patients." (PMID 27854304, 2016). "It is interesting that albumin decreases as CRP increases in different tumor types, which explains the prognostic value of mGPS in various cancers." (PMID 27537502, 2016).
cancer (continued). "Recently, the Glasgow prognostic score (GPS), which is based on C-reactive protein (CRP) and albumin levels as well as reflects inflammation and nutritional status, was used as a prognostic indictor for numerous cancers." (PMID 26754834, 2016). "To date, several measurements of systemic inflammatory response, such as NLR, platelet-to-lymphocyte ratio, C-reactive protein, and serum albumin, have been investigated in cancer patients." (PMID 26469891, 2015). "SAA is known to be an acute-phase protein and is more sensitive than CRP for predicting the prognosis of cancer." (PMID 26264146, 2015). "When comparing to the reference value from general population, cancer patients showed numerically higher ferritin, sTfR, CRP and hepcidin level." (PMID 26517509, 2015). "This possibly implies that cancer patients are more likely to be exposed to inflammatory condition based on higher ferritin, CRP and hepcidin level, and more likely to encounter an iron restricted erythropoiesis based on higher sTfR level." (PMID 26517509, 2015). "It is noteworthy that C-reactive protein levels are prognostic in cancer, as demonstrated by the Glasgow Prognostic Score; however, this has not been evaluated in a phase 1 patient population and deserves further consideration." (PMID 25719834, 2015). "Increasing age, male gender, history of cancer, high C-reactive protein (>3mg/l), neutrophil and platelet counts were independently associated with an increase in cancer mortality (all p<0.001)." (PMID 25730322, 2015). "When comparing to reference range from the general population, 39 cancer patients in this study showed numerically higher ferritin, sTfR, CRP, and hepcidin level." (PMID 26517509, 2015). "Since the links between cancer and inflammation were reported and accepted, clinical value of CRP in various malignancies was noticed by more and more researchers." (PMID 26235332, 2015). "Inflammation-related markers such as absolute white blood cell count, C-reactive protein (CRP), cytokines, platelet-to-lymphocyte ratio (PLR), and NLR have been shown to be associated with specific outcomes in cancer patients." (PMID 26137435, 2015). "Some cancer cells express CRP and secrete interleukin-6 and interleukin-8, which stimulate liver CRP production." (PMID 26717416, 2015). "Increasing age, male gender, hospital admission, history of cancer, high C-reactive protein (>3mg/l), neutrophil and platelet counts were independently associated with an increase in all-cause mortality (all p<0.001)." (PMID 25730322, 2015). "Increasing age, male gender, increasing deprivation, hospital admission, history of cancer, high C-reactive protein (>10mg/l), neutrophil and platelet counts were independently associated with an increase in all-cause mortality (all p<0.001)." (PMID 25730322, 2015). "Elevated levels of C-reactive protein (CRP), which is a marker of systemic inflammation, was found to be a predictor of low survival in patients with various cancers, including ESCC." (PMID 26390126, 2015). "There is strong evidence that elevated CRP levels have an impact on the growth and progression of cancers, including EC." (PMID 26390126, 2015). "IL-6 is an important proinflammatory cytokine that plays a key role in the development of cancer and closely correlates with CRP levels." (PMID 26084991, 2015). "From a simple comparison of measurements to reference value in general population, we found that cancer patients showed numerically higher ferritin, sTfR, CRP and hepcidin." (PMID 26517509, 2015). "The basis of the independent prognostic value of C-reactive protein, albumin and neutrophil count over all disease states (and platelets in cancer) is likely to be complex." (PMID 25730322, 2015). "Not surprisingly, serum ferritin level correlated more strongly to CRP and hepcidin compared to sTfR in cancer patients." (PMID 26517509, 2015).
cancer (continued). "C-reactive protein (CRP) is one of the most investigated markers of inflammation in the context of cancer detection and prognosis." (PMID 26284119, 2015). "In this study, we retrospectively analyzed the prognostic power of CRP/Alb ratio in 367 eligible patients with SCLC at our cancer center." (PMID 26084991, 2015). "As a secondary aim, we also wanted to investigate if there was an association between 25OHD levels and survival time and compare with the well-established markers albumin and CRP, often used in clinical practice to estimate survival time in cancer patients." (PMID 26018761, 2015). "By multivariate analysis, when adjusted for other variables, including cancer stage, CRP/Alb ratio independently predicted the overall survival of patients with SCLC (p = 0.025)." (PMID 26084991, 2015). "The GPS based on CRP and serum albumin reflects the systemic inflammatory response to cancer, and its proven prognostic value in cancer patients augments the contributory role of inflammation to tumor aggressiveness." (PMID 25966773, 2015). "First, traditional inflammatory markers such as white blood cell count (WBC) and CRP have shown prognostic value in patients prior to developing a cancer or when they are already suffering from a detected cancer." (PMID 25861154, 2015). "We suggested that the combination of the mGPS and CRP/Alb ratio would better distinguish the survival differences of cancer patients." (PMID 25934640, 2015). "Among all cancer patients, those with increased C-reactive protein levels had a significantly worse outcome than those with low levels of inflammatory markers." (PMID 26637394, 2015). "Another possibility is that cancer cells increase production of inflammatory proteins, which leads to high CRP levels in cancer patients." (PMID 25999661, 2015). "Increasing age, male gender, increasing deprivation, hospital admission, history of cancer, high C-reactive protein (>10mg/l), neutrophil and platelet counts were independently associated with an increase in cardiovascular mortality (all p = 0.001)." (PMID 25730322, 2015). "Model 2 utilized the same predictors as Model 1, with the following 3 additional binary variables: CRP ≥ 200 mg/L or extent of consolidation on chest X-ray ≥ 2/3, use of mechanical ventilator/vasopressors, and presence of cancer." (PMID 25514976, 2014). "Elevated CRP is a significant predictor of lower survival rates in patients with several cancers, including esophageal, colorectal, hepatocellular, pancreatic, urinary bladder, renal, ovarian, and cervical cancer, after surgical resection." (PMID 24829560, 2014). "GPS, which is a combination of CRP and albumin levels, reflects the effects of systemic inflammatory response and the process of nutritional decline in advanced cancer." (PMID 24885814, 2014). "The inflammatory marker, C reactive protein has been proposed to also be a biomarker for adaptive immune responses in cancer patients with a possible application in time based chemotherapy." (PMID 24957270, 2014). "CRP is an acute-phase reactant, and elevated baseline serum CRP levels have also been found to be a poor prognostic factor in cancers of many types." (PMID 24454777, 2014). "CRP can serve as an additional prognostic predictor for survival and post-treatment monitoring in cancer patients." (PMID 24829560, 2014). "The serum SCC-Ag and CRP levels were measured at the time of cancer diagnosis, 3 to 6 months after treatment with clinical disease-free, and at the time of recurrence." (PMID 25061977, 2014). "Bivariate analysis showed that serum albumin, CRP, ESR, ALP, iron, LDH, white blood cell count, hemoglobin, and ferritin levels were associated with cancer." (PMID 24762986, 2014). "Overall, measurement of plasma CRP is simple, rapid, cost effective, suitable and provides valuable information for patients with cancer." (PMID 24800842, 2014).